CD44 (CD44 molecule (IN blood group))
Diseases named in the same sentence as CD44 in open-access papers (continued):
Sharing a sentence is not in itself a finding about the gene and the disease.
cancer (continued). "Further analysis revealed that Gal-4 interacts with c-MET and CD44 on the cell surface, facilitating cancer progression." (PMID 39664377, 2024). "In 1994, Guo and colleagues first noticed an elevation in soluble CD44 levels in the serum of individuals with colon and stomach cancer." (PMID 38544254, 2024). "Still, the expression of CD44 promotes spheroid formation, while versican facilitates the interaction between CD44 and hyaluronan and, thus, regulates the peritoneal adhesion and spread of cancer spheroids." (PMID 38398174, 2024). "To determine CD44 levels within normal and cancer samples, we investigated CD44 gene expression pattern in pan-cancer based on publicly available gene expression data." (PMID 38590654, 2024). "From a mechanistic point of view, CD44 has been shown to mediate multiple cancer signaling pathways." (PMID 38542115, 2024). "Several efforts have already been made to target CD44v6, one of the CD44 isoforms, in several cancer types in a variety of clinical trials." (PMID 38761292, 2024). "A critical early event in cancer metastasis involves the interaction between cancer cells and ECs, where CD44 and its ligand hyaluronic acid (HA) play key roles." (PMID 39758992, 2024). "We also detected in OEP and OLP increased levels of Met and Cd44, which are the markers of cancer stem cells that we identified in human clear cell kidney tumors." (PMID 38512983, 2024). "Rab27A expression is upregulated in MDA-MB-231 grown as mammospheres compared with those grown as adherent cells, and reducing Rab27A expression decreases mammosphere formation by lowering the proportion of cancer-initiating CD44+/CD24−/low cells." (PMID 38543182, 2024). "An increasing amount of literature indicates CD44, and especially the CD44v isoforms, as a marker for cancer stem cells." (PMID 38881904, 2024). "These normal biological roles for CD44 also make its overexpression highly beneficial when it occurs in cancer cells." (PMID 38539529, 2024). "This same study also demonstrated, using in vitro studies, that silencing of the CD44v3 isoform leads to reduced activation of some common signaling molecules and reduced cell growth, hinting at a potential direct role in cancer cell growth for CD44 isoforms." (PMID 38539529, 2024). "In head and neck cancers, cells exhibiting EMT properties also exhibit increased expressions of cancer stem cell (CSC) markers such as CD44, CD133 and SOX2." (PMID 38606479, 2024). "For example, more cancer-associated fibroblasts (CAFs) infiltrated the high-risk group of FRM, and the expression of CD44 was also upregulated in this cluster." (PMID 38534739, 2024). "Soluble GPNMB has critical functions; for example, it interacts with CD44 to promote cancer cell stemness and metastasis." (PMID 38585871, 2024). "AA combined with PD1 monoclonal antibody increases CD11b+CD44+ PD-L1+ cell infiltration to enhance antigen presentation, resulting in an enhanced immune anti-cancer effect." (PMID 38822322, 2024). "Recent advances in understanding the complex interactions of CD44 with ligands have led to the development of CD44 not only as an important cancer stem cells (CSCs) marker but also as a potential cancer therapeutic target." (PMID 38783892, 2024). "CD44 is highly expressed in many cancers and is also recognized as a cancer stem cell (CSC) biomarker." (PMID 38542115, 2024). "Cancer cells were stained intensely with antibodies for CD44, as were normal epithelial cells in the peritumor tissue; however, less intense but clearly visible staining was also characteristic of the stromal cells of the organ mucosa." (PMID 38540309, 2024). "For exploring the effect of CD44 on TME, CIBERSORT deconvolution algorithm was adopted for calculating overall correlation landscape of CD44 with immune cell infiltration in 33 cancer types." (PMID 38590654, 2024).
cancer (continued). "This pathology is mainly brought about by cancer-associated stem cells (CSCs) which are abundant in the TME and express high levels of CD44 on their surface." (PMID 38816670, 2024). "Consistent with findings from other studies, we found decreased expression of the cancer stem cell markers CD44, ALDH1, and OCT4 in OECM-1 and SAS cells under hypoxic conditions compared to normoxic conditions." (PMID 38904007, 2024). "The sphere formation assay, number of side population cells, and CD271 + /CD44 + cells were detected by flow cytometry to identify the cancer stem cell properties." (PMID 38254118, 2024). "As one of the important functions of CD44, its regulation of cancer‐related pathways is pleiotropic, including cancer initiation, aggressive behavior, and stemness." (PMID 38783892, 2024). "While the precise role that CD44 plays in cancer development and resistance to chemotherapy agents remains to be fully determined, the protein provides three avenues for possible novel therapeutic approaches." (PMID 38539529, 2024). "In particular, isolated CD44+CD133+ cancer stem cells exhibited higher chemoresistance compared to unsorted cells." (PMID 39518936, 2024). "The migratory subtype also exhibits similar characteristics to those of cancer stem cells (CSC) with expression of known CSC markers (CD44, SOX9, ALDH1A3 and VEGFA) and those for tissue migration, angiogenesis, EMT and the TNFA pathway." (PMID 38892065, 2024). "The intensity of green fluorescence was therefore a reflection of CD44 expression levels on the surface of live, cultured, cancer cells." (PMID 39201626, 2024). "For example, combinations of different markers, such as CD133, CD44, CD24, and ALDH, have been reported to be associated with cancer stem cell properties; however, highly sensitive and specific markers for CSCs remain elusive." (PMID 38831317, 2024). "Further research is required to elucidate this relationship to aid clinicians in managing CD44-positive cancer patients." (PMID 38542115, 2024). "By elucidating the involvement of CD44 in facilitating cancer cell engraftment onto vascular ECs, we have here unveiled potential therapeutic avenues for disrupting this process." (PMID 39758992, 2024). "The LYVE-1 expression pattern implies the transfer of HA from tissues into the lymphatic vessel, where it is internalised and degraded and provides a chemotactic substrate for CD44+ leukocytes and cancer cells." (PMID 38791985, 2024). "These engineered EVs deliver chemotherapeutic drugs to drug-resistant cancer cells through CD44-mediated targeting." (PMID 39513123, 2024). "We also go over the importance of cancer stem cell-related gene expression patterns, specifically CD44 and ALDH1A1 expression, in therapy resistance and disease progression." (PMID 39452555, 2024). "Attenuation of cancer stem cell (CSC)-like properties was associated with the downregulation of stemness factors such as ALDH1, CD44, Nanog and Oct4." (PMID 38646654, 2024). "The obtained CS-HAD NPs (100–120 nm) were able to selectively deliver siRNA to cancer cells with overexpressed CD44." (PMID 39408718, 2024). "CD44, a cell surface glycoprotein, mediates adhesion and communication between cancer cells and vascular ECs." (PMID 39758992, 2024). "This review aims to discuss the prognostic and predictive importance of CD44 in cancer diseases, especially in CRC." (PMID 38672650, 2024). "In this study, the detection of the CD44 cancer biomarker under dynamic conditions was reported using a single-mode optical fiber ball resonator biosensor." (PMID 38544254, 2024). "Collectively, these data show that CD44 is involved in prolactin mediated iron uptake in cancer cells." (PMID 39201626, 2024). "HCT-8 cell-derived spheroids were initially constructed as a model for tumoroid formation, exhibiting a higher proportion of CD44+CD133+ double-positive cancer stem cell markers compared to the adherent control cells." (PMID 39518936, 2024).
cancer (continued). "Cancer cells move through the vascular area by a sequence of less strong adhesive connections involving selectins found on endothelial cells and CD44, CEA, and PODXL on tumor cells’ surfaces." (PMID 39338413, 2024). "In OC, IL6 via JAK/STAT promotes the expression of CD44, also known as Homing Cell Adhesion Molecule (HCAM), a transmembrane glycoprotein associated with cancer cell stemness." (PMID 39766086, 2024). "The naked HA shell promoted the cellular uptake of NPs by CD44‐presenting cancer cells and TAMs that shuttle them to the hypoxic regions where drug payload is delivered." (PMID 39217459, 2024). "The cell adhesion molecule CD44 is weakly expressed in normal tissues, usually associated with CD133+ cells in cancer metastases." (PMID 38664641, 2024). "A study by Eliaz and Szoka demonstrated the efficacy of HA-modified liposomes in delivering chemotherapeutic agents to CD44-overexpressing cancer cells, indicating its potential as a targeted delivery mechanism." (PMID 38672650, 2024). "CD44 is a transmembrane glycoprotein that modulates cancer stemness and metastases and promotes proliferation and invasion." (PMID 39473666, 2024). "CD44 is particularly expressed on the surface of activated lymphocytes and tumor cells, and its activation promotes cell proliferation, cancer cell growth, and metastasis." (PMID 39768177, 2024). "CD44 acts as a receptor for hyaluronic acid, and previous studies indicate that CD44 expressed on both ECs and cancer cells engages in cell-cell adhesion through a sandwich structure involving hyaluronic acid." (PMID 39758992, 2024). "Several studies have demonstrated a positive link between elevated levels of the CD44 protein and the progression of cancer." (PMID 38544254, 2024). "Targeting CD44 + cells (an indicator of cancer stem cells) with therapeutic strategies, such as chemotherapy drugs, has proven effective in CRC treatment." (PMID 38167453, 2024). "Alternatively, will macrophages release ferrous iron into the environment to be immediately coupled with hyaluronan prior to uptake by the cancer cells through CD44?" (PMID 39201626, 2024). "Our results indicated that the expression of SOX2, Oct4, Nanog, and CD44 was highly noticeable in these three cancer cell lines, while treatment with hinokitiol effectively reduced the expression of these stemness-related proteins." (PMID 38612715, 2024). "In order to get one step closer to clinical usage, a dynamic platform for biosensing the cancer biomarker CD44 using a single-mode optical fiber-based ball resonator biosensor was designed, constructed and evaluated in this work." (PMID 38544254, 2024). "CD44 functions as a surface biomarker that specifically enhances the proliferation of cancer stem cells, which play a crucial role in the progression of cancer." (PMID 38544254, 2024). "HA binds to CD44, a cell surface receptor, and this enhances the migration, proliferation, and invasion of cancer cells." (PMID 38544822, 2024). "We have identified frequently used markers for the determination of cancer cells and CSCs: Axl, CD44, CD90, CD117, CD276, EGF, PD-L1, PD-1, Sox2." (PMID 38664641, 2024). "MiR-23b which targets MARCKS, inhibits the proliferation capacity and CD44 (cancer stem cell marker) expression of BCCs." (PMID 39000239, 2024). "Extensive studies have revealed that CD44 mediates cancer initiation and progression through interactions with its ligands, including but not limited to HA, OPN, serglycin, CS, the MMPs family, and FN." (PMID 38783892, 2024). "The goal of this work was to develop and assess a biosensing platform that is both economical and simple to produce, with the ability to detect a specific cancer biomarker of interest, such as the CD44 protein in real-time." (PMID 38544254, 2024). "CD44 is well-known as a hyaluronic acid receptor highly expressed on the cell surface of malignant cancer cells." (PMID 39136001, 2024).
cancer (continued). "While we did not test the targeting activity of our nanosystem in the present work, we believe that the nanobiohybrid particles can potentially target CD44 overexpressed cancer cells." (PMID 39279556, 2024). "The CD44 glycoprotein is a surface marker of CSCs that activates signaling pathways, promoting cancer cell metastasis, adhesion, migration, and drug resistance." (PMID 38672650, 2024). "The modification of liposomal surfaces with HA appears to significantly augment the suppression of CD44-overexpressing cancer cells." (PMID 38337294, 2024). "CD44 is a well-known biomarker for CSCs and regulates metastasis and drug resistance in many cancers." (PMID 39145451, 2024). "CD44 shows high expression within various cancer cells, which is related to cancer genesis and invasiveness, so it is considered as a molecular marker of cancer stem cells (CSCs)." (PMID 38590654, 2024). "Further, TIMER2.0 platform was adopted for analyzing differential CD44 expression within cancer and non-carcinoma samples from TCGA dataset." (PMID 38590654, 2024). "Firstly, the CD44 mRNA expression within different non-carcinoma samples was analyzed through HPA database." (PMID 38590654, 2024). "CD44 plays important roles in cell adhesion, migration, and signaling, and its overexpression is believed to contribute to cancer cell invasion and metastasis." (PMID 37759771, 2023). "The identification and targeting of CD44-positive CSCs hold promise for improving cancer treatment outcomes." (PMID 37958796, 2023). "Additional markers such as CD151, CD147, and drug transporter proteins (ABCG2/CD338), (MDR1/ABCB1/CD243) have been reported to interact and co-express with CD44 on cancer cells." (PMID 36834918, 2023). "For the treatment against refractory tumors, such as the recurrence after chemotherapy, the treatment should target the emerging specific population such as CD44 (or CD44v9) and proliferative cancer cells." (PMID 37523119, 2023). "Western blot analysis revealed that SQLE depletion substantially reduced the expression of cancer stemness‐related proteins, including CD44, BMI1, SOX2, and KIF‐4, in ALDHhigh primary HNSCC cells." (PMID 37490552, 2023). "CD44 is a transmembrane glycoprotein involved in aggregation, proliferation, and migration in both normal and cancer cells and also in angiogenesis." (PMID 37173926, 2023). "The same phenotype has been observed in cancer: Nrp-1 expression on CD8+ T cells was accompanied by elevated expression of CD44, CD69 and CD25, but also by several co-inhibitory molecules such as PD-1, CTLA-4, Lag-3 and Tim-3." (PMID 38019895, 2023). "In particular LS1034 xenografted cancer cells demonstrated an elevated expression of CD44 mRNA isoform 3 compared to cultured cells, whereas ESPR1 expression was reduced and ESRP2 expression was essentially enhanced in the LS1034 xenografts." (PMID 38106992, 2023). "CD44, one of the E-selectin ligands expressed on migrating cancer cells, is known to interact with the soluble protein E-selectin in these processes." (PMID 37046797, 2023). "CD44 is one of the important cancer stem cell markers in many cancers including colon cancer, breast cancer, prostate cancer, and lung cancer." (PMID 37092398, 2023). "CD133+ cells isolated from CRC cell populations have been shown to mimic properties of CRC cancer stem cells and CD44+ cells exhibit enhanced tumorigenicity and cell proliferation in CRC." (PMID 37950151, 2023). "Notwithstanding, most studies on CD44 were restricted to specific cancer types, obscuring its exact role in tumorigenesis." (PMID 37117249, 2023). "The main HA receptor is CD44 protein (cluster of differentiation 44), a single-chain trans-membrane glycoprotein, which is also one of the most relevant markers of cancer stem cells (CSCs) in many types of cancer." (PMID 36830841, 2023).
cancer (continued). "In one study, the redox-active ferrocene (Fc) containing Fc-GQD-HA, a biocompatible formulation, was found to target specifically CD44 over-expressing cancer cells with ~ threefold oxidative-stress-mediated Hela cell death." (PMID 38112935, 2023). "Cancer cells that undergo EMT can acquire stem cell-like properties and show an increase in CD44 expression, which is frequently used as a molecular marker for cancer stem cells (CSCs)." (PMID 36571444, 2023). "CD44v6 as CD44 isoform is expressed in epithelial cells as well as proliferating cells during embryonic development and in cancer cells." (PMID 37491225, 2023). "Recent meta-analyses have provided conclusive evidence for a predictive value of CD44 expression in cancer patients." (PMID 37958796, 2023). "and the results revealed by CancerSEA database denoted the correlation of CD44 with malignant phenotype and functional states, further indicating it can serve as a potential therapeutic target in cancer management." (PMID 37117249, 2023). "They argue that BMP-4 boosts the expression of cancer stem cell markers, like CD44 and Nanog, in MDA-MB-231 cells." (PMID 38139368, 2023). "The comparison between the normal adjacent kidney tissues and the various stages of ccRCCs showed a consistently significant increase in the expression of CD44 levels in different stages of cancer." (PMID 37174052, 2023). "On the other hand, CD44 in SW480 colon cancer cells can promote EMT in various cancers by upregulating mesenchymal genes and downregulating epithelial phenotype-related genes." (PMID 37835592, 2023). "The NPs enabled the targeted delivery of DXM to inflammatory regions via the cancer cell membrane-expressed adhesion receptor CD44, which inhibits the expression of inflammation-related components." (PMID 36895440, 2023). "In this review, I focus on the significance of CD44 in malignancy and discuss the dichotomous function of the hyaluronan/CD44 axis in cancer progression." (PMID 37958796, 2023). "In these cases, HA is used for targeting cancer cells because it can bind overexpressed receptors such as CD44 and RHAMM on cancer cells." (PMID 38028018, 2023). "Cpd3 alone significantly reduced the CSC content defined as CD133+CD44+ or CD133+CXCR4+ cancer cells, whereas gemcitabine treatment increased the CSC content." (PMID 38012687, 2023). "CD44 is a transmembrane proteoglycan that is overexpressed in many cancer cell types, including CSCs." (PMID 38102651, 2023). "Most research on the prognostic role of OPN and CD44 in cancer focuses on protein expression levels." (PMID 38067149, 2023). "A comprehensive analysis of malignant ascites identified the genomic alterations and significant amplifications of cancer driver genes, including CD44." (PMID 37489367, 2023). "Of these, CD44 is an established stemness marker in several cancer types, where it promotes proliferation, invasiveness and radio-resistance." (PMID 37344645, 2023). "The results showed that HDAC3 silencing reduced the phosphorylation of CDK1 Y15 and STAT3 Y705 followed by reduction of CD44 and Sox2, which resulted in the impairment of cancer cell stemness." (PMID 37743465, 2023). "CD44 interaction with OCT4 signaling plays a critical role in the acquisition of cancer stem-cell properties, including chemoresistance, in cancer cells." (PMID 36838713, 2023). "Accumulating evidence indicates that CD44 is not only a marker for CSC in BC but also in other types of cancer." (PMID 36899854, 2023). "Alternative splicing of CD44 pre-mRNA and the essential role of CD44 isoforms in cancers are highlighted in this review." (PMID 38106992, 2023). "The major experimentally tested regulators of alternative splicing of CD44 in cancer have been described earlier by Prochazka and co-authors." (PMID 38106992, 2023). "CD44+ cells isolated from cancer patients were capable of initiating tumor growth when transplanted into immunocompromised mice and showed increased resistance to radiochemotherapy." (PMID 37853413, 2023).